MMP12 (matrix metallopeptidase 12)
Diseases named in the same sentence as MMP12 in open-access papers (continued):
Sharing a sentence is not in itself a finding about the gene and the disease.
emphysema (continued). "The previous study has elucidated that IL-4 produced by basophils induces the differentiation of accumulated monocytes into MMP-12 producing IMs in a mouse model of emphysema induced by elastase." (PMID 34425800, 2021). "The expression level of MMP-12 mRNA in the whole lung of LILRB4−/− mice in the emphysema model was significantly higher than that in wild-type mice." (PMID 34425800, 2021). "A growing body of evidence indicates that MMP9 and MMP12, largely secreted from macrophages, are implicated in the breakdown of lung tissues in COPD and emphysema." (PMID 32973788, 2020). "It seems that MMP-12 plays a crucial role in this phenomenon: in a murine model it was shown that the enzyme breaks down the ECM component elastin, and MMP-12-null mice exposed to cigarette smoke avoided emphysema development." (PMID 30658596, 2019). "GM-CSF enhanced exudative macrophage expression, and 8 dpi BAL fluid levels of MMP12, or macrophage elastase, which is best known for its requirement for the development of smoke-induced emphysema in mice." (PMID 29304863, 2018). "MMP‐12, also known as macrophage elastase, is involved in the development of emphysema, and a targeted deletion of MMP‐12 confers resistance to cigarette smoke‐induced emphysema." (PMID 30058137, 2018). "A previous study suggests that KO of Mmp12 protects mice from emphysema as it plays an important role in CS-induced airway remodeling." (PMID 29899396, 2018). "Animal studies have shown that mice with abnormalities in the activation and signaling of TGF-β1 develop pulmonary emphysema through increased expression of the extracellular macrophage metalloproteinase Mmp12 in the lung." (PMID 28784933, 2017). "Presence of MMP-12 in sputum and activity in patients with COPD are directly associated with the extent of emphysema measured by means of lung function and computed tomography." (PMID 28848433, 2017). "The majority of studies in animal models have attested the importance of MMPs in parenchymal destruction in emphysema, especially the MMP-12; other proteases such as neutrophil elastase from the serine proteases family are described in humans emphysema." (PMID 27445433, 2016). "Several studies in animals and humans have provided evidence that MMP12 (human macrophage elastase) is important in airway inflammation and the development of emphysema." (PMID 27891067, 2016). "Here, we also observed increased tissue inflammation, iBALT formation, MMP12 expression and emphysema development in old mice exposed to CS for 3 months." (PMID 26284585, 2016). "Administration of anti-IL-4 Abs was found to reduce MMP12 expression and emphysema in α-GalCer administered mice." (PMID 26811900, 2016). "First, it was shown that these emphysema-like features are substantially (~50 %) reduced by deletion of MMP12 in βENaC-Tg mice." (PMID 27456476, 2016). "Over long periods of time, β6 KO mice over produce macrophage-derived matrix metalloprotease MMP12, leading to emphysema and destruction of pulmonary tissue." (PMID 27505057, 2016). "MMP-12 has been most extensively investigated and shown to play a consistent critical role in animal models of emphysema." (PMID 27455234, 2016). "MMP12 up-regulation is also demonstrated to play a critical role in emphysema to lung cancer transition that is facilitated by inflammation." (PMID 27891067, 2016). "Mouse models with MMP-12-deficient macrophages and pharmacological inhibition of MMP-12 showed that MMP-12 activity plays an important role in the development of emphysema." (PMID 27363862, 2016). "The deficiency of integrin αvβ6-mediated TGF-β activation leads the mice to spontaneously develop emphysema at 14M of age in a MMP12 dependent manner." (PMID 27689529, 2016). "In mice, IL-17 is essential for the development of emphysema from long term CS exposure by activating the IL-17 → Ccl-2 → MMP-9 → MMP-12 signaling axis." (PMID 27363862, 2016).
emphysema (continued). "Along with this increase in macrophage numbers, we observed an increase in matrix metalloproteinase 12 (Mmp12), a macrophage-derived protease important in emphysema development in WT and βENaC-Tg mice." (PMID 26066648, 2015). "Recently, it has been shown that Mmp12 and neutrophil elastase also mediate emphysema in βENaC-Tg mice." (PMID 26066648, 2015). "Some authors have suggested that MMP-9 and MMP-12 are relevant to emphysema, are involved in experimental models of elastase, and are involved in the degradation of collagen fibers." (PMID 26122092, 2015). "The proteases NE and MMP12 have been clearly established to be key factors in the development of protease imbalance and emphysema." (PMID 25793977, 2015). "We show that vitamin D deficiency accelerates lung function changes upon CS exposure consistent with an increased lung compliance and TLC, early signs of emphysema and enhanced expression of MMP-12." (PMID 26376849, 2015). "Even though the majority of animal models of emphysema have reinforced the importance of MMP-12, there are many studies in patients who implicate the importance of collagenases, such as MMP-1, -8 and -13 in this disease." (PMID 26052708, 2015). "Studies on animal models showed that decreased TGF- β signaling results in emphysema through alterations in macrophage MMP12 expression." (PMID 24587150, 2014). "Although transgenic upregulation of MMP-1 in mice leads to emphysema, knockout of the MMP-12 gene prevents the development of emphysema in mice exposed to cigarette smoke, implicating both of these proteases in the process." (PMID 24792232, 2014). "Even though the rBmTI-A treatment administered after emphysema development resulted in a decrease in MMP-12 positive cells in the PPE-rBMTIA compared with the PPE-VE groups, the PPE-rBMTIA group continued to have higher values compared with the control groups." (PMID 24886716, 2014). "For example, the expression of MMP-12, an elastolytic enzyme, has also been shown to be increased in individuals with emphysema." (PMID 24792232, 2014). "Building upon the long known association between emphysema development in smokers and congenital deficiency of α1-AT, Shapiro and colleagues established the critical role of MMP-12 (macrophage elastase) in emphysema development." (PMID 23450717, 2013). "Interventions directed at inhibiting MMP-9 activity, either alone or in combination with MMP-12 blockers, should be investigated for their potential to attenuate the development or progression of emphysema." (PMID 27234393, 2013). "Though BALF MMP-12 levels were altered amongst the study cohorts (1.7±0.1 ng/ml in control, 2.0±0.3 ng/ml in smokers, 11.8±4.7 ng/ml in emphysema; p<0.004 by Kruskal-Wallis test), only controls and emphysema subjects showed a significant intergroup difference." (PMID 23441181, 2013). "Over-expression of MMP12 in lung alveolar type II epithelial cells induced local inflammation, emphysema and lung tumor." (PMID 23613996, 2013). "The metalloelastase, MMP-12, was shown to be required for cigarette smoke-induced emphysema in mice." (PMID 23441181, 2013). "Other laboratories have built upon the MMP-12 work, documenting the importance of additional MMPs in emphysema pathogenesis." (PMID 23450717, 2013). "The collagenase MMP-1, the gelatinase MMP-9 and the metalloelastase MMP-12 are of particular interest in emphysema pathogenesis." (PMID 23441181, 2013). "MMP12 plays an important role in mouse emphysema, and MMP12 was found specifically induced in IL-4-stimulated M2 macrophages." (PMID 23533311, 2013). "Transgenic mice over-expressing MMP-1 develop emphysema, whilst MMP-12 knockout mice are protected from emphysema despite prolonged cigarette smoke exposure." (PMID 23228114, 2012). "CB NPs were unable to potentiate elastase-induced emphysema, although they induced inflammation and MMP-12 expression per se and potentiated elastase-induced perivascular/peribronchial infiltration." (PMID 22849372, 2012).
emphysema (continued). "Elastase administration increased BAL cellularity, histological inflammation, HO-1, IL-1β and macrophage MMP-12 expression and induced emphysema." (PMID 22849372, 2012). "After 6 months of cigarette smoke exposure we found that IL-17RA was critical for the induction of CCL2, macrophage recruitment, MMP12 expression, and emphysema in mice." (PMID 21647421, 2011). "Taken together, these data demonstrate that cigarette smoke is a potent Th17 adjuvant and that IL-17RA signaling is required for chemokine expression necessary for MMP12 induction and tissue emphysema." (PMID 21647421, 2011). "This is consistent with observations of increased MMP-12 activity in the lungs of patients with COPD and with observations in a rodent model of disease where MMP-12 knock-outs are protected against smoking-induced emphysema." (PMID 20078883, 2010). "MMPs, particularly increased levels of MMP-9 and MMP-12, are involved in CS-mediated airspace enlargement/alveolar wall destruction (emphysema)." (PMID 20663150, 2010). "Macrophages and DCs are the main sources of MMP-12, a matrix metalloproteinase that has been described as the key proteolytic enzyme in the development of CS-induced emphysema in mice." (PMID 19445658, 2009). "Because MMP-12 is one of the major proteinases impicated in the development of pulmonary emphysema, we studied the presence of MMP-12 in lung tissue by immunohistochemistry." (PMID 19445658, 2009). "Lower numbers of macrophages and DCs, combined with impaired release of MMP-12, also resulted in an attenuation of CS-induced pulmonary emphysema in NK1-R-/- mice." (PMID 19445658, 2009). "Whilst, animal studies have shown that MMP-12 is important in cigarette smoke induced emphysema, the relevance of MMP-12 in human disease is controversial." (PMID 18001475, 2007). "Previous studies have shown that contribution of MMP-12 to smoke induced emphysema is probably enhanced by indirect effects, such as inactivation of AAT and MMP-12 mediated recruitment of neutrophils to the lung." (PMID 18001475, 2007). "Mice who are unable to activate latent TGFβ develop emphysema via alterations of MMP12, suggesting that disordered activation relates to the pathogenesis of COPD." (PMID 17054776, 2006). "Studies from MMP-12 knock-out mice indicate that MMP-12 is a key mediator in cigarette smoke-induced emphysema." (PMID 16359550, 2005). "To elucidate the possible mechanisms by which pulmonary emphysema develops in CS-exposed (scid) mice, we measured mRNA levels of matrix metalloproteinase-12 (MMP-12), perforin and granzyme B in the lungs of air- and CS-exposed animals by RT-PCR." (PMID 16359546, 2005). "In an animal model of tobacco smoke-induced tissue matrix degradation, not only neutrophil enzymes but also macrophage-derived enzymes such as MMP-12 are important for the development of emphysema-like lesions." (PMID 15522115, 2004). "We have shown here that IP-10 and MIG, two chemokines that are secreted from lung lymphocytes of participants with emphysema, upregulate specifically MMP12 and thus favor a proteolytic microenvironment that facilitates lung destruction." (PMID 15526056, 2004). "Studies from both humans and mice therefore firmly suggest the importance of MMP12 in the pathogenesis of emphysema." (PMID 15526056, 2004). "MMP12 is critical in the formation of emphysema in Scnn1b-Tg+ model." (PMID 40496925, 2025). "In addition to the well-documented role of AAT deficiency in pulmonary emphysema, genetic variations in MMP genes, particularly MMP-12, have been implicated in emphysema." (PMID 40422205, 2025). "Furthermore, Mmp12 activates protease-activated receptor-1, upregulates placenta growth factor, and leads to pulmonary emphysema." (PMID 38532405, 2024). "MMP-12 belongs to the matrix metalloproteinases family, which contributes to the remodeling of the small airways and to the proteolytic degradation of the alveolar wall matrix, leading to emphysema." (PMID 38612871, 2024).
emphysema (continued). "Also, TNF-α over-expresser mice developed emphysema with increased expression of MMP12 and the pro-inflammatory chemokines." (PMID 38771844, 2024). "M2 profiles in COPD promote the production of proteolytic enzymes, such as MMP9 and MMP12, inducing the activation of mucin-related genes and contributing to lung tissue damage, emphysema, and the development of airway obstruction, while inducing wound repair and inflammation resolution." (PMID 38891820, 2024). "In particular, the AMs release matrix metalloprotease (MMP)-12, which promotes emphysema." (PMID 37592330, 2023). "Consequently, MMP-12 and neutrophil elastase −/− mice were drastically protected from cigarette smoke induced emphysema due to reduced propensity for elastin degradation." (PMID 37001705, 2023). "However, a recent study proposed that IMs are the primary MMP-12 producers, and that the IL-4/IM/MMP-12 axis is important for the development of emphysema." (PMID 37592330, 2023). "However, the absence of neutrophil elastase did not lead to complete protection from cigarette smoke-induced emphysema as was demonstrated for the depletion of macrophage elastase (MMP-12), which was accompanied by reduced macrophage accumulation in the lungs." (PMID 35288557, 2022). "Of note, mice deficient in MMP-12 do not develop emphysema, human MMP-12 single-nucleotide polymorphisms are strongly associated with severe to very severe COPD and MMP-12 inhibitors such as AS111793 or MMP408 provide significant protection against emphysema." (PMID 35053420, 2022). "Our findings suggest that TRPML3 represents a key regulator of MMP-12 clearance by alveolar macrophages and may serve as therapeutic target for emphysema and chronic obstructive pulmonary disease." (PMID 35031603, 2022). "Furthermore, altered macrophage population, abnormal elastin deposition, and elevated levels of the elastin-modifying MMP12 were observed, which are similar to the markers of emphysema." (PMID 34829987, 2021). "Thus, our results indicate that ascariasis can provoke the development of emphysema-like COPD in mice potentially through the persistent elevated expression of MMP-12 however further comprehensive evaluation is needed." (PMID 34914687, 2021). "We have shown that the Mmp12 gene is critical for triggering the in utero SHS-aggravated elastase-induced emphysema, HDM-induced asthma, and urethane-induced lung cancer, with significant up-regulation of this gene in the lungs of the exposed female mouse offspring." (PMID 34912233, 2021). "Several studies have shown that Mmp12 plays a role in emphysema development in humans." (PMID 34912233, 2021). "Our results suggest that LILRB4, which is upregulated on lung IMs in both human COPD patients and a mouse elastase-induced emphysema model, has a protective effect against the formation of emphysematous lesions through the attenuation of MMP-12 production, mainly by IMs." (PMID 34425800, 2021). "Notably, a previous report demonstrated that inhibition of MMP-9/MMP-12 considerably suppresses emphysema morphology and small airway remodeling." (PMID 34784929, 2021). "This upregulated LILRB4 may have a protective effect against emphysema formation, possibly through decreasing MMP-12 expression in the lungs." (PMID 34425800, 2021). "Our analyses of both the human lung samples and LILRB4-deficeint mice suggest that LILRB4, which is upregulated on lung IMs in COPD patients, may have a protective effect against emphysema formation through decreasing MMP-12 expression." (PMID 34425800, 2021). "Matrix metalloproteinase-12 (Mmp12) is upregulated by cigarette smoke (CS) and plays a critical role in extracellular matrix remodeling, a key mechanism involved in physiological repair processes, and in the pathogenesis of emphysema, asthma, and lung cancer." (PMID 34912233, 2021). "Thus, the expression of factors associated with tissue destruction and healing, including MMP-12, MMP-9, and Cathepsin S, was also increased in emphysema mice." (PMID 32681029, 2020).
emphysema (continued). "Importantly, the mRNA levels of IL-1β, TNF-α, IL-8, IRF-5, IL-18, IFN-γ, TGF-β, matrix metalloproteinase-9 (MMP-9), and MMP-12 were decreased in the FMT-treated emphysema group compared with the emphysema group." (PMID 32681029, 2020). "However, with regard to MMP-12, there have been rather few reports on the mechanisms behind the destruction of lung tissue structure, airway remodeling, and emphysema formation in patients with COPD." (PMID 31143784, 2019). "Senescent cells secrete SASP mediators, such as MMP-12, TGFβ1, and IL-33, affecting the extracellular matrix homeostasis, which in combination with the loss of regenerative capacity of senescent AECII progenitors, leads to alveolar destruction and emphysema." (PMID 31428695, 2019). "Furthermore, expression of MMP12 is increased in the lungs of COPD patients and has been implicated in pathogenesis of emphysema." (PMID 29975735, 2018). "MMP-12 is better studied in conditions of lung pathology, including emphysema, and alveolar macrophages are known to release MMP-12 in METs during infection, suggesting that protease release from leukocytes may contribute to this disease process." (PMID 30459195, 2018). "Consistent with this notion, MMP12 knockout mice are protected from developing emphysema." (PMID 29975735, 2018). "In addition, the inactivation of MMP‐12 or neutrophil elastase confers resistance to cigarette smoke‐induced emphysema in mice." (PMID 30058137, 2018). "MMP-12 SNP affects the enzyme activity, and protects against emphysema in COPD." (PMID 28848433, 2017). "The proteinase MMP-12 is an important enzyme in the development and progression and emphysema." (PMID 27363862, 2016). "We hypothesized that the IFN-γ and/or IL-4 production by activated iNKT cells enhanced MMP12 expression and the development of emphysema." (PMID 26811900, 2016). "This unbiased approach identified Mmp12, but no other candidates previously implicated in emphysema formation, as a strongly upregulated gene in the lungs from βENaC-Tg mice." (PMID 27456476, 2016). "Matrix metalloproteinases (MMP)-12 is an important proteinase in the development of emphysema." (PMID 26811900, 2016). "Data obtained from a large multiple cohort association study, linked the variation of MMP-12 with lung function in smokers and the risk of developing COPD, while, in animal models of COPD, the deletion of MMP-12 in mice exposed to cigarette smoke protects these animals from emphysema." (PMID 26126526, 2015). "MMP12 is known to be a key mediator involved in the development of emphysema." (PMID 25793977, 2015). "Indeed, increased lung concentrations of NE, MMP-1, MMP-9, and MMP-12 have been found in CS-exposed mice and emphysema patients, and thus excessive proteolytic activity must be tightly regulated." (PMID 25962837, 2015). "Both serine proteases and matrix metalloproteases are expressed in human emphysema, and animal models involving the instillation of neutrophil elastase and knockout mice for metalloprotease 12 (MMP-12) have been used to clarify the pathogenesis of this disease." (PMID 24886716, 2014). "MMP12 expression may be induced by smoking and trigger inflammation, leading to emphysema and lung cancer in mouse models of inflammatory triggers of oncogenesis." (PMID 25114662, 2014). "Both MMP-9 and MMP-12 are likely to be involved in ozone-induced emphysema." (PMID 24260479, 2013). "We did not, however, find any associations between the MMP1 and MMP12 SNPs and emphysema or lung functions decline." (PMID 23734748, 2013). "Following the development of the MMP-12 knockout mouse, the group demonstrated that smoke-exposed mice deficient in MMP-12 do not develop parenchymal changes consistent with emphysema." (PMID 23450717, 2013). "Finally, the expression of major actors of cigarette smoke-induced emphysema, such as HO-1, MMP-12 and IL-1β was increased in our elastase-instilled animals, supporting the relevance of the model." (PMID 22849372, 2012).